LAMB3 (laminin subunit beta 3)
Diseases named in the same sentence as LAMB3 in open-access papers (continued):
Sharing a sentence is not in itself a finding about the gene and the disease.
cancer (continued). "By examining the relationship between LAMB3 expression and prognosis, immune microenvironment, and DNA methylation in cancer patients, we used a variety of bioinformatics to investigate the potential role of LAMB3 in pan-cancer." (PMID 37577750, 2023). "Secondly, we investigated the possibility of LAMB3 functioning as a biomarker for the diagnosis of pan-cancer." (PMID 37577750, 2023). "We further investigated the expression of LAMB3 in different cancer cell lines and normal tissues through the BioGPS database, and we found that LAMB3 had high expression in a small number of normal cell strains." (PMID 37577750, 2023). "The findings demonstrated that the majority of cancer types exhibited a significant upward trend in the expression of LAMB3." (PMID 37577750, 2023). "The correlation between LAMB3 differential expression and pan-cancer molecular subtype is explored from the TISIDB database." (PMID 37577750, 2023). "The prognostic significance of LAMB3 in various cancers and clinical subtypes was investigated using Kaplan-Meier and Cox regression analysis." (PMID 37577750, 2023). "We used multiple databases, including TCGA, CCLE, genotype tissue expression (GTEx), human protein mapping (HPA), and cBioPortal to analyze LAMB3 expression levels and prognosis in pan-cancer." (PMID 37577750, 2023). "Specifically, the molecules involved in cancer-related pathways, including LAMB3, KEAP1, Bid, EGFR, Bcl-XL, Bcl-2, and PAX8, were all regulated by JorA." (PMID 37587470, 2023). "The expression of LAMB3 in various immune and molecular subtypes of human cancer was examined using the TISIDB database." (PMID 37577750, 2023). "The findings demonstrated that the most of cancer types had significantly distinct expression patterns of LAMB3 in various immune and molecular subtypes." (PMID 37577750, 2023). "The expression of LAMB3 in the molecular and immune subtypes of pan-carcinoma was then investigated to learn more about its potential mode of action." (PMID 37577750, 2023). "Among these, LAMB3 has been shown to play a role in cancer development, and the involvement of laminin-332 (assembled by three subunits, α3, β3, and γ2) in cancer pathogenesis has been extensively reported." (PMID 36081907, 2022). "Further study will be needed to elucidate the detailed mechanism underlying PCMT1/LAMB3 interation and dissect the regulatory mechanism that drives the changes in PCMT1 levels during the process of cancer cell detachment." (PMID 35033172, 2022). "Then, we analyzed the upregulated top five differentially expressed genes between the paracancer tissue and the cancer tissue, which included LAMB3, FN1, KRT17, KRT19, and ANXA1." (PMID 35428170, 2022). "As cell cycle dysregulation is an important event for cancer proliferation, we further investigated the function of LAMB3 in the cell cycle using flow cytometry analysis." (PMID 32039003, 2019). "For instance, miR-218 can inhibit cancer cell metastasis and invasion by targeting LAMB3 in cervical squamous cells." (PMID 31708963, 2019). "Previous studies have reported that LAMB3 is also targeted by some miRNAs, such as miR-1298 and miR-329, regulating cancer progression." (PMID 32039003, 2019). "Rescue assay demonstrated that miR-24-3p exerted its anti-cancer role by suppressing LAMB3 expression." (PMID 32039003, 2019). "Functional studies confirmed that regaining LAMB3 in miR-24-3p-overexpressing cells abrogated the anti-cancer effect induced by miR-24-3p and that LAMB3 inhibition abrogated the cancer-promoting effects induced by the miR-24-3p inhibitor." (PMID 32039003, 2019). "Some targets of miR-218, such as ROBO1, RICTOR, BIRC5 and LAMB3, have been reported to participate in many cancer signaling pathways, such as the ERK/MAPK, Wnt/β-catenin, and Notch pathways." (PMID 29717030, 2018). "In particular, LAMB3, involved in the focal adhesion pathway, is a potential biomarker of cancer invasion and metastasis." (PMID 29426928, 2018).
cancer (continued). "Other target genes of miR-218 that have been identified by previous researchers including BMI1, LAMB3, and LASP1 and the expressions of these genes were associated with the invasion or prognosis in different cancer types." (PMID 28298809, 2017). "Our data demonstrated that LAMB3 was directly regulated by miR-218 and functioned as an oncogene, contributing to cancer cell migration and invasion in cervical SCC." (PMID 23483249, 2013). "LAMB3 was expressed in many epithelial tissues and was involved in tumor microenvironment by increasing carcinoma cell migration." (PMID 23320911, 2013). "A loss-of-function assay using siRNA analysis was performed to examine the function of LAMB3 in cancer cells." (PMID 23159910, 2012). "Our data clearly showed that LAMB3 functioned as an oncogene and strongly contributed to cancer cell migration and invasion." (PMID 23159910, 2012). "In addition, high expression of other key genes like PAK2, LAMB3 and LAMA3 is also associated with malignant tumors." (PMID 37694778, 2024). "LAMB3 is known to exhibit tumorigenic effects in multiple types of cancer, including HNSCC." (PMID 38957320, 2024). "However, LAMB3 activates the PI3K/Akt signaling pathway to support cancer cell survival, invasion, and metastasis." (PMID 39223142, 2024). "Besides LAMB3, prior reports discuss other significantly up-regulated genes from our study as they pertain to various cancers." (PMID 38957320, 2024). "At the same time, we observed that the expression of LAMB3 was significantly correlated with the different immune subtypes of 20 cancer types (C1: wound healing, C2: IFN-gamma dominance, C3: inflammatory, C4: lymphocyte depletion, C5: immune quiet, C6: TGF-b dominance)." (PMID 37577750, 2023). "We also discussed the potential correlation between LAMB3 expression and the immune checkpoint (ICP) gene, immune cell infiltration level, microsatellite instability (MSI), and tumor mutation load (TMB) in 33 cancers." (PMID 37577750, 2023). "Our findings reveal an important role for LAMB3 in different cancer types." (PMID 37577750, 2023). "Furthermore, laminins LAMBC2 and LAMB3 support cancer progression and resistance to gemcitabine—one of the main chemotherapeutics used in PDAC patients." (PMID 37296850, 2023). "In most cancers, LAMB3 protein expression showed an upward trend over normal tissues." (PMID 37577750, 2023). "This study provides new insights into the role of LAMB3 in anti-cancer immunotherapy." (PMID 37577750, 2023). "Be that as it may, most exploration on the job of LAMB3 in growths is restricted to explicit kinds of disease, LAMB3 the job in human pan-cancer prognosis and immunology is rarely systematically analyzed." (PMID 37577750, 2023). "As a result, we hypothesize that LAMB3 could be a novel immunotherapy target or a pan-cancer biomarker that could predict the response to immunotherapy or produce promising therapeutic outcomes." (PMID 37577750, 2023). "LAMB3 is emerging as a potential therapeutic target for cancer due to its oncogenic role." (PMID 36612197, 2022). "Furthermore, analysis of LAMB3 expression in adjacent normal tissues than in tumors of the breast across various cancer types of patients indicated that such correlation between LAMB3 gene expression and ER status." (PMID 36293530, 2022). "At the same time, LAMB3 is an oncogene that participates in cancer cell migration and invasion." (PMID 31485443, 2019). "With the initiation of PDAC, LAMB3 mainly existed in stroma and cytoplasm of cancer cells." (PMID 30598639, 2018). "In conclusion, our findings could suggest that LAMB3 contributes to cancer cell migration and invasion in PTC via c-MET/Akt signaling." (PMID 29426928, 2018).
cancer (continued). "Interestingly, expression of only LAMB3, and not FAK, is upregulated by KRAS; yet silencing of either FAK or LAMB3 recapitulates miR-1298-induced cell death in KRAS-dependent cancer cells." (PMID 29891810, 2018). "Elucidation of LAMB3-regulated cancer pathways may provide novel therapeutic strategies to control PTC metastasis." (PMID 29426928, 2018). "We chose to further investigate HE4’s regulation of LAMC2 and LAMB3, since these two genes code for chains of laminin-332, a secreted heterotrimer that has been well-described to promote aggression and metastatic properties in diverse cancers." (PMID 29404274, 2017). "LAMB3 that expressed in many epithelial tissues could induce carcinogenesis by increasing carcinoma cell migration and disturbing tumor microenvironment." (PMID 23320911, 2013). "In addition, LAMB3 is involved in the invasion and metastasis of certain types of cancer." (PMID 37577750, 2023). "Additionally, in prostate, thyroid, colorectal, and other cancers, LAMB3 may aid in the growth of tumors." (PMID 37577750, 2023). "However, the role of LAMB3 in human pan-cancer immunology and prognosis is still poorly understood." (PMID 37577750, 2023). "Similarly, LE-LE cancer cells could signal through adhesive ligand-receptor pairs LAMB3-ITGA6_ITGB4 and LAMB3-ITGA6_ITGB1, and inflammatory ligand-receptor pairs MIF-CD74_CD44." (PMID 37596273, 2023). "Importantly, we first linked PCMT1 with the ECM protein LAMB3 and demonstrated that the PCMT1-LAMB3 interaction activates the integrin-FAK-Src pathway to promote cancer cell adhesion, migration and invasion and that these effects can be reversed by treatment with a PCMT1-blocking antibody." (PMID 35033172, 2022). "However, LAMB3 gradually translocated into the nucleus of cancer cells at advanced PDAC stages." (PMID 30598639, 2018). "Eight hub genes (MMP1, MMP7, MMP13, LAMC2, LAMB3, PLAU, COL7A1, and SPP1) were upregulated in both HNSCC and LSCC, suggesting a significant role in cancer progression." (PMID 38707175, 2024). "LAMB3, a regulator of the integrin‐FAK‐Src pathway, promotes cancer progression by anoikis resistance." (PMID 36507553, 2023). "The close connection between LAMB3 and TME in human cancers is also demonstrated by the correlation between LAMB3 and TMB and MSI." (PMID 37577750, 2023). "Of all the datasets investigated, LAMA3, LAMA5, LAMB3 and LAMC2 were found to be commonly upregulated in cancer when compared to adjacent tissue samples as well as in CCA tissues and cell lines." (PMID 38114514, 2023). "Quantitative RT–PCR analysis was used to verify that SOX1 controlled the expression of genes related to pathways in cancer, such as LAMB3, FN1, and HES1, and the focal adhesion pathway, including LAMB3 and FN1." (PMID 37190139, 2023). "But there are also a few cancers, such as BLCA, where high LAMB3 expression means a better prognosis." (PMID 37577750, 2023). "LAMB3 has been shown to activate the PI3K/Akt signaling pathway, promoting cancer cell proliferation, migration and invasion in vitro." (PMID 35340765, 2022). "We demonstrated that through LAMB3, PCMT1 activates integrin-FAK-Src signaling to enhance cancer cell adhesion, migration, and invasion and promote metastasis formation." (PMID 35033172, 2022). "In the 178 PC patients, the LAMB3, FN1, KRT17, KRT19, and ANXA1 were also upregulated in cancer tissue, compared with adjacent tissues and normal tissues." (PMID 35428170, 2022). "LAMC2 together with laminin subunit beta-3 (LAMB3) and laminin subunit alpha-3 (LAMA3) constitutes laminin-332, which is secreted by epithelial tumor cells, thereby regulating cancer invasion." (PMID 34612783, 2021). "Laminin subunit beta 3 (LAMB3) and PDPNs are thought to be pEMT markers and to be related to cancer metastasis." (PMID 34421348, 2021).
cancer (continued). "Our histopathological evidence has shown that COL12A1 and FN1 are expressed from stromal cells, THBS2, and VCAN from stromal and cancer cells, while ITGA2, LAMB3, and LAMC2 are expressed solely from the cancer cells." (PMID 34007003, 2021). "LAMB3 and LAMA4 belong to the laminin subunit family and have been reported to be involved in the metastasis and invasion of some types of cancer." (PMID 34456632, 2021). "Since overexpression of LAMB3 abrogated the anti-cancer effects induced by miR-24-3p mimics and silencing of LAMB3 abrogated the oncogenic effects induced by miR-24-3p inhibitor, we concluded that miR-24-3p might exert anti-tumor effects by regulating LAMB3 expression in vitro." (PMID 32039003, 2019). "Podoplanins (PDPN) and laminin subunit beta 3 (LAMB3) were considered as p-EMT markers and have been suggested to be related to cancer cell metastasis." (PMID 31238980, 2019). "The elevation of tumor invasion is supported by our sequencing results that demonstrated TNFα up-regulates invasion-related genes of MMP1, MMP9, MMP14, LAMB3, and FGF2 which all have been previously reported to increase OSCC cancer invasion." (PMID 30018735, 2018). "Additionally, MYOSLID drives metastasis by regulating epithelial–mesenchymal transition markers such as LAMB3 and Slug while promoting RAB13-mediated cytoskeletal remodeling and enhancing cancer cell invasion." (PMID 40149492, 2025). "Considering that LAMB3 and LAMC2 are established prognostic markers in various cancer types, our findings may also have implications for endothelial cells within tumor microenvironment." (PMID 39201392, 2024). "Among the genes positively co-expressed with LAMA3, LAMB3, and LAMC2, there are important proteins which may change cancer cell behaviour and cancer progression in different tumours." (PMID 37779898, 2023). "The overexpressed integrin α (ITGA) subfamily genes ITGA2 and ITGA3 are predicted to be involved in cancer-related pathways such as PI3K-Akt signaling pathway and FA interacting with ECM genes such as laminin (LAMB3, LAMA3, and LAMC2) and collagen (COL10A1, COL12A1)." (PMID 34262595, 2021). "Fifteen members of cancer pathways, including FOS, TGFα, FZD8, MMP1, laminin subunit gamma 2, PTGS2, laminin subunit beta 3, ITGA2, laminin subunit alpha 3, VEGFC, WNT2B, heat shock protein 90 beta family member 1, WNT5B, FGF5 and WNT3A, were up-regulated in the MC group." (PMID 30482199, 2018). "LAMB3, along with LAMA1, LAMA3 and LAMC2, was enriched in pathways involved in cancer." (PMID 28904855, 2017). "In addition to PLAUR and LAMB3, S100A10 was another gene upregulated by both hypoxia and hypoglycaemia based on our array analysis, and has been shown to be important in cancer cell invasion and metastasis through colocalization with uPA/PLAUR system." (PMID 25079072, 2014). "Seven up-regulated genes including CYC1, MIF, LAMB3, TUBB2, UBE2C and TRAP1 had been previously proposed as candidate common cancer biomarkers based on a previous extensive comparison among various cancers and normal tissues which did not, however, include NPC or NP." (PMID 18570662, 2008). "Furthermore, LAMB3 interacts with proteins such as collagen VI and osteopontin, binding to integrins like ITGB1 (integrin subunit β 1), which supports ECM remodeling and promotes the migration and invasion of cancer cells." (PMID 40149492, 2025). "Recent studies have more evaluated LAMB3 and TOP2A expression in malignant tumors rather than in CSCS." (PMID 36415640, 2022). "Among the 16 common cancer biomarkers identified as highly predictive by the previous study which did not include NPC samples, 6 genes (CYC1, MIF, LAMB3, TSTA3, TUBB2, and UBE2C) were found to be highly expressed in NPC by the study." (PMID 18570662, 2008). "In contrast to LAMB3, the role of LAMB4 in cancer has not been intensively investigated." (PMID 36081907, 2022).
tumor (74 papers, 2005 to 2025). "LAMB3 expression was significantly positively associated with PTC tumour tissue size (p = 0.001, r = 0.49) and T stage (p = 0.017, r = 0.339)." (PMID 41139196, 2025). "Overexpression of LAMB3 has been strongly associated with lymph node metastasis, where it enhances tumor cell dissemination by increasing motility and invasion, ultimately facilitating the establishment of secondary metastatic sites." (PMID 40149492, 2025). "Among the genes resulting from the primary tumor, LAMB3 was already associated with nervus and brachial plexus neoplasms, conditions closely related to MPNST." (PMID 39409151, 2024). "For example, LAMB3 is very highly expressed in MBC epithelial tumor cells, with more than five peak-to-gene links associated with its promoter." (PMID 37685859, 2023). "The relationship between LAMB3 expression, various immune cell infiltration, immune checkpoints, tumor mutational load, microsatellite instability, and DNA methylation was examined using the TCGA database." (PMID 37577750, 2023). "In addition, LAMA3 and LAMB3, encoding the α3 and β3 chains of Laminin‐332, were also highly expressed in the tumor basal stem‐like cell region compared to normal epithelial areas." (PMID 40470730, 2025). "Similarly, it has also been shown that the overexpression of LAMB3 in CRC is associated with tumor metastasis and poor prognosis, of which the mechanism is mainly through the AKT–FOXO3/4 axis to the pro-tumorigenic role." (PMID 36741692, 2022). "Furthermore, higher LAMB3 expression was notably associated with larger and advanced tumour grade in this study, indicating a potential disruption of laminin expression in PTC, which maybe associated with disease invasiveness." (PMID 41139196, 2025). "Our findings suggest that LAMB3 expression significantly increases in PTC and it is associated with tumor size and T stage." (PMID 41139196, 2025). "LAMB3 expression in PTC significantly correlated with tumour size (p = 0.001, r = 0.49) and T-stage (p = 0.017, r = 0.339), but not with other clinicopathological factors." (PMID 41139196, 2025). "In particular, LAMB3 participates in the infiltration and migration of pancreatic, lung, head and neck, prostate, and gastric tumours." (PMID 41139196, 2025). "By contributing to BM breakdown, LAMB3 allows tumor cells to breach this structural barrier, a key event in metastatic progression." (PMID 40149492, 2025). "And we validated LAMB3 upregulation via PTC tissue microarray analysis, where it was indeed associated with PTC tumor size and T stage." (PMID 41139196, 2025). "LAMA3, LAMB3 and LAMC2 genes encode for laminin-332, which is related to tumor invasiveness and metastasis and is considered a factor of poor prognosis." (PMID 38473784, 2024). "A number of studies have revealed that LAMB3 is involved in cellular invasion and metastasis processes in several tumor types." (PMID 39218967, 2024). "LAMB3 has been previously studied as a tumor-related gene and is known to mediate cell-cycle arrest and apoptosis." (PMID 38510118, 2024). "In terms of specific L/R pairs, based on the spatial transcriptome expression assessment, stress-like tumor cells were likely to interact with CD44+ IgG1 PCs by secreting LAMB3." (PMID 37138324, 2023). "In summary, we have performed the first comprehensive and systematic analysis of LAMB3 and cross-validated it using different databases, patient samples, and tumor cell lines." (PMID 37577750, 2023). "LAMB3 plays an important role in tumor immunity by affecting tumor infiltration immune cells, TMB and MSI." (PMID 37577750, 2023). "The differential gene expression levels between tumor and adjacent tissue displayed in the box plot showed that LAMB3, KRT14, KRT16, KRT17, and KRT6B expression levels were significantly (p < 0.001) higher in normal tissues than in tumors." (PMID 36293530, 2022).